SNHG15 (small nucleolar RNA host gene 15)
Synonyms: FLJ38860; MYO1GUT; Linc-Myo1g; C7orf40
Gene: Long non-coding RNA gene on chromosome 7 (44,983,019 to 44,986,961, reverse strand). Ensembl gene ENSG00000232956.
Gene Ontology:
Biological process: RNA processing
Cellular component: nucleolus
Diseases named in the same sentence as SNHG15 in open-access papers:
SNHG15 is named in the same sentence as 67 diseases in open-access papers, as found by Europe PMC text mining. Sharing a sentence is not in itself a finding about the gene and the disease. The quoted sentences say what the papers report.
breast cancer (20 papers, 2019 to 2024). A primary or metastatic malignant neoplasm involving the breast. "SNHG15 plays significant roles in regulating cell proliferation and invasion via different potential mechanisms, and the abnormal expression of SNHG15 is associated with pathological features in breast cancer patients." (PMID 39519115, 2024). "Recent studies have suggested that SNHG15 is involved in cancer occurrence and progression and is linked with poor survival in many human malignancies, including colorectal cancer, breast cancer, lung cancer, ovarian cancer and pancreatic cancer." (PMID 37958584, 2023). "In breast cancer, elevated levels of SNHG15 were associated with proliferation, migration, and invasion of breast cancer cells through acting as a competing endogenous RNA (ceRNA) to sponge miR-211-3p." (PMID 33572758, 2021). "SNHG15 has been linked to lower survival in a lot of human malignancies, including breast cancer, colorectal cancer, gastric cancer, glioma, hepatocellular cancer, lung cancer, osteosarcoma, ovarian cancer, pancreatic cancer, renal cell carcinoma and thyroid cancer." (PMID 35629174, 2022). "The down-regulation of these genes in responding to SNHG15 expression was further confirmed in at least two breast cancer cell lines." (PMID 39519115, 2024). "In this study, we identified a novel function of SNHG15 to suppress the transcription of the MTSS1 gene in breast cancer cells." (PMID 39519115, 2024). "Investigation of the endogenous levels of SNHG15 in four breast cancer cell lines indicated that T47D cells expressed the highest levels of SNHG15, while BT-549 cell lines expressed relatively low levels of the lncRNA." (PMID 37958584, 2023). "explored the molecular mechanism of SNHG15 in breast cancer, revealing that SNHG15 acted as a miR-211-3p sponge in carcinogenesis." (PMID 37056344, 2023). "In this study, we report that in breast cancer cells, SNHG15 is one of the lncRNAs that interacts with IMP1." (PMID 37958584, 2023). "lncRNA small nucleolar RNA host gene 15 (SNHG15) is the lncRNA located on human chromosome 7 and has been demonstrated upregulation in a variety of tumors, such as breast cancer, hepatocellular carcinoma, and nasopharyngeal carcinoma." (PMID 35733923, 2022). "There is strong evidence that SNHG15 silence apparently depresses the invasion and epithelial-mesenchymal transition and proliferation, migration, while promotes apoptosis of breast cancer cells." (PMID 33482820, 2021). "In breast cancer, it has been shown that SNHG15 functions as a ceRNA to sponge miR-211-3p, thereby promoting cell proliferation, migration, and invasion and inhibiting apoptosis." (PMID 33243205, 2020). "Recent studies reported an aberrant expression of SNHG15 in various malignant tumors including liver cancer, breast cancer, gastric cancer, lung cancer, glioma and colorectal cancer." (PMID 32633324, 2020). "Previous studies reported high expression levels of SNHG15 in various cancer types, such as gastric cancer, colorectal cancer, osteosarcoma, glioma, lung cancer and breast cancer, and similar conclusions were confirmed by the evidences from TCGA cohort." (PMID 32633324, 2020). "Our results that IGF-regulated lncRNAs, including SNHG7 and SNHG15, are important for biology, enriched in breast cancer subtypes, and correlate with survival are consistent with recent studies." (PMID 32444795, 2020). "According to the literature, HOXA11AS is upregulated in breast cancer cell lines (e.g., SNHG15) and stimulates breast cancer invasion and metastasis by regulating the epithelial-mesenchymal transition." (PMID 31319040, 2020). "Dysregulation of lncRNAs, including DSCAM-AS1, SNHG15, and HOXA1-AS, has been implicated in breast cancer development and progression, and is correlated with prognosis." (PMID 31310241, 2019).
breast cancer (continued). "Since the MTSS1 gene plays a vital role in breast cancer metastasis, we hypothesized that SNHG15-induced breast carcinogenesis could be largely contributed to by the down-regulation of MTSS1 mRNA." (PMID 39519115, 2024). "SNHG15 has been often demonstrated to have a sponging function, binding, and disabling various miRNAs to upregulate the expression of oncogenic genes in glioma, breast cancer, and lung cancer." (PMID 37880732, 2023). "Functional assays indicated that silencing SNHG15 in T47D and MDA-MB-231 cells decreased cell proliferation potential, while ectopically expressed SNHG15 in BT-549 cells significantly promoted cell proliferation and invasive ability, indicating the oncogenic role of SNHG15 in breast cancer cells." (PMID 37958584, 2023). "In addition, in breast cancer it has been proved that by sponging miR-211-3p, SNHG15 contributes to proliferation, migration and invasion and by sponging miR-141, it promotes proliferation, invasion and autophagy in osteosarcoma cells." (PMID 35629174, 2022). "Interestingly, small nucleolar RNA host gene 15 (SNHG15) has been reported to serve as a morbigenous lncRNA in human cancers, such as lung cancer, breast cancer, ovarian cancer and prostate cancer." (PMID 33506255, 2021). "LncRNA small nucleolar RNA host gene 15 (SNHG15) was found to be upregulated in a variety of cancers including breast cancer, lung cancer, and hepatocellular carcinoma, and the overexpression of SNHG15 was related to the enhanced proliferation and metastasis abilities of cancer cells." (PMID 33817274, 2020). "Beyond CRC, the dysregulation and oncogenic role of SNHG15 has been indicated in various types of cancer, including gastric and hepatocellular carcinoma, osteosarcoma, as well as pancreatic and breast cancers." (PMID 31014355, 2019). "FISH (fluorescence in situ hybridization) experiments indicated that substantial quantities of SNHG15 were localized in the nuclei of breast cancer cells expressing either ectopic SNHG15 or endogenous SNHG15, suggesting that SNHG15 could possess a nuclear function." (PMID 39519115, 2024). "Our study not only demonstrated that SNHG15-mediated MTSS1 suppression promotes breast cancer progression but also revealed a molecular mechanism by which an lncRNA like SNHG15 could serve as a regulator to repress gene transcription via interacting with the gene promoter." (PMID 39519115, 2024). "The ability of SNHG15 to promote cancer cell progression was verified in breast cancer cell lines, in which the ectopic expression of SNHG15 increased cell proliferation and invasion, while these potentials could be rescued by knocking down SNHG15." (PMID 39519115, 2024). "SNHG15 could regulate cisplatin resistance in breast cancer by sponging miR-381 expression." (PMID 35432537, 2022). "We first silenced DDX5 mRNA and performed qRT-PCR tests in breast cancer cells, which showed that the down-regulation of DDX5 reduced levels of SNHG15." (PMID 39519115, 2024). "Small nucleolar RNA host gene 15 (SNHG15) is a typical lncRNA that has been revealed to be upregulated as a tumor facilitator in NSCLC, CRC, breast cancer, pancreatic cancer, and GC." (PMID 34771549, 2021).
osteosarcoma (17 papers, 2017 to 2024). A usually aggressive malignant bone-forming mesenchymal neoplasm, predominantly affecting adolescents and young adults. "Knockdown of SNHG15 significantly promoted the apoptosis of osteosarcoma cells, mainly due to a resulting increase in expression of apoptosis-related protein Bax, cleaved caspase-3, and downregulation of anti-apoptotic Bcl-2." (PMID 37056344, 2023). "The involvement of SNHG15 was also responsible for the proliferation, autophagy, and invasion of osteosarcoma cells." (PMID 32318335, 2020). "A positive relationship was observed between GFRA1 and SNHG15 in DXR-resistant osteosarcoma tissues." (PMID 33817274, 2020). "In osteosarcoma, SNHG15 promotes cell proliferation, autophagy, and migration by acting as a ceRNA for miR-141." (PMID 32318335, 2020). "The luciferase activity was dramatically reduced in miR-381-3p and SNHG15 WT co-transfected groups compared with that in miR-381-3p and SNHG15 MUT co-transfected groups, suggesting that miR-381-3p was a direct target of SNHG15 in osteosarcoma cells." (PMID 33817274, 2020). "SNHG15 depletion contributed to the inhibitory effect of DXR on osteosarcoma tumor growth through the miR-381-3p/GFRA1 axis in vivo." (PMID 33817274, 2020). "In summary, SNHG15 contributed to DXR resistance of osteosarcoma cells through promoting autophagy via the miR-381-3p/GFRA1 axis in vivo and in vitro." (PMID 33817274, 2020). "Collectively, miR-381-3p was a direct target of SNHG15 in osteosarcoma cells, and it was negatively modulated by SNHG15." (PMID 33817274, 2020). "For example, in osteosarcoma, SNHG15 can directly bind miR-141 as a “molecular sponge” to promote osteosarcoma expression and cancer growth." (PMID 32733556, 2020). "Taken together, SNHG15 contributed to DXR resistance of osteosarcoma cells through the miR-381-3p/GFRA1 axis in vivo." (PMID 33817274, 2020). "The enrichment of SNHG15 was enhanced in osteosarcoma cells compared with that in human osteoblast cells hFOB." (PMID 33817274, 2020). "Small nucleolar RNA host gene 15 (SNHG15) contributed to invasion, proliferation, migration, and autophagy by negatively regulating miR-141 in osteosarcoma through elevating the levels of ATG5 and LC3-II." (PMID 30266744, 2018). "SNHG15 was upregulated in DXR-resistant osteosarcoma tissues and cell lines." (PMID 33817274, 2020). "The expression of SNHG15 was upregulated in DXR-resistant osteosarcoma tissues (n = 30) compared with that in DXR-sensitive osteosarcoma tissues (n = 30), suggesting that it might play a crucial role in DXR resistance of osteosarcoma cells." (PMID 33817274, 2020). "Meanwhile, SNHG15 knockdown enhanced DXR sensitivity of two DXR-resistant osteosarcoma cells." (PMID 33817274, 2020). "Besides, the expression of SNHG15 was further upregulated in DXR-resistant osteosarcoma cells compared with that in their parental cells." (PMID 33817274, 2020). "Based on these findings, we hypothesize that SNHG15 might regulate proliferation, invasion and autophagy in osteosarcoma cells by sponging miR-141." (PMID 28720111, 2017). "Similarly, SNHG15 was also overexpressed in colorectal cancer, thyroid carcinoma and osteosarcoma." (PMID 32126023, 2020). "However, the role of SNHG15 and its molecular mechanism in osteosarcoma (OS) cells are largely unknown." (PMID 28720111, 2017). "To further illustrate the regulatory relationship among SNHG15, miR-381-3p, and GFRA1 in osteosarcoma cells, we first analyzed the linear relationship between the expression of SNHG15 and GFRA1 in DXR-resistant osteosarcoma tissues." (PMID 33817274, 2020). "One of the top ranked lncRNAs, SNHG15, has not been experimentally linked to blood cancer; however, its regulation of the ubiquitin-proteasome system and its established oncogenic role in osteosarcoma suggest it may be a promising lncRNA for blood cancers." (PMID 31379598, 2019). "MiR-381-3p was a direct target of SNHG15, and GFRA1 bound to miR-381-3p in osteosarcoma cells." (PMID 33817274, 2020).
osteosarcoma (continued). "Nevertheless, the role of SNHG15 in the doxorubicin (DXR) resistance of osteosarcoma cells has not been fully addressed." (PMID 33817274, 2020). "Existing literature pointed out that SNHG15 could exert oncogenic functions on the progression of colon cancer, NSCLC, colorectal carcinoma, and osteosarcoma via acting as a competing endogenous RNA (ceRNA) or interacting TFs12,15,45–47." (PMID 32655137, 2020).
gastric cancer (15 papers, 2017 to 2025). A primary or metastatic malignant neoplasm involving the stomach. "On the one hand, E2F1 and MYC can activate the expression of SNHG15, forming positive feedback and promoting the occurrence of gastric cancer." (PMID 39210921, 2024). "For example, lncRNA SNHG15 is upregulated in gastric cancer, and silencing SNHG15 constrains the propagation, migration, and invasion and promotes apoptosis of gastric malignant cells." (PMID 35813862, 2022). "Subsequently, SNHG15 was investigated in tumor, and the SNHG15 expression was upregulated in cancers and high SNHG15 expression predicted poor prognosis, for instance, gastric cancer, lung cancer, colorectal cancer, and glioma." (PMID 34734088, 2021). "In gastric cancer, SNHG15 upregulation promotes cell proliferation and invasion by modulating the expression of MMP2/MMP9." (PMID 33243205, 2020). "Moreover, SNHG15 can promote the proliferation and invasion of gastric cancer cells by regulating the expression of MMP2 and MMP9 proteins." (PMID 38526609, 2024). "For example, lncRNA SNHG15 was upregulated in gastric cancer (GC) and E2F1 could interact with the promoter of SNHG15, leading to an increase in its expression." (PMID 39119602, 2024). "Besides, knockdown of SNHG15 significantly inhibited cell proliferation and invasion and promoted apoptosis, whereas forced expression of SNHG15 exhibited the opposite effects on gastric cancer cells via regulating MMP2 and MMP9 protein expression." (PMID 28720111, 2017). "Small nucleolar RNA host gene 15 (SNHG15), a novel lncRNA, is identified as a key regulator in tumorigenesis and progression of various human cancers, including colorectal cancer (CRC), gastric cancer (GC), pancreatic cancer (PC) and hepatocellular carcinoma (HCC)." (PMID 31774607, 2020).
pancreatic cancer (15 papers, 2017 to 2024). "In pancreatic cancer, the knockdown of SNHG15 resulted in G0/G1 phase block, thereby inhibiting cell proliferation in vitro, similar to the roles of SNHG15 in ovarian cancer." (PMID 37056344, 2023). "It was found that the level of SNHG15 was significantly higher in both plasma and cancer tissues from patients with pancreatic cancer." (PMID 34439315, 2021). "Such actions could involve alterations of repressive epigenetic marks since lncRNAs were reported to recruit or to interact with epigenetic writers including DNMTs, and SNHG15 in particular was described to interact with EZH2 in pancreatic cancer." (PMID 37880732, 2023). "SNHG15 could act as an oncogene in pancreatic cancer, further research found that SNHG15 knockdown inhibited proliferative capacities and suppressed apoptotic rate of pancreatic cancer cells in vitro, and impaired in vivo tumorigenicity." (PMID 35330729, 2022). "Nevertheless, the biological function and regulatory mechanism of SNHG15 remain unclear in pancreatic cancer (PC)." (PMID 29137412, 2017). "Moreover, a high level of SNHG15 was also significantly correlated with lymph node metastasis, higher tumor stage, and shorter overall survival, suggesting that SNHG15 is a promising biomarker for the diagnosis and prognosis of pancreatic cancer." (PMID 34439315, 2021). "In pancreatic cancer, SNHG15 can also bind to the enhancer of zeste homolog 2 and inhibit the expression of p15 and the Kruppel-like factor 2 by zeste homolog 2-mediated H3 lysine 27 trimethylation modification and finally promote the proliferation of pancreatic cancer cells." (PMID 32733556, 2020). "It has been demonstrated that elevated expression of SNHG15 is significantly related to tumour size, TNM stage, and lymph node metastasis in pancreatic cancer patients." (PMID 33243205, 2020). "Thus, although SNHG15 and HOTAIR have similar functions in pancreatic cancer, they differ in terms of target genes and their mechanisms of action." (PMID 29137412, 2017).
colorectal cancer (13 papers, 2019 to 2024). A primary or metastatic malignant neoplasm that affects the colon or rectum. "Our results describe a role for the MYC-regulated SNHG15 locus in colorectal cancer, role dependent on the lncRNA encoded by this bifunctional gene." (PMID 31014355, 2019). "c-Myc also upregulates the expression of lncRNA SNHG15, which promotes colorectal cancer development and mediates drug resistance." (PMID 39830506, 2024). "In colorectal cancer, diverse experimental methods have confirmed that SNHG15 interacted with the Slug zinc finger domain and affected Slug protein levels in a post-transcriptional dependent manner." (PMID 37056344, 2023). "It has been documented that SNHG15 works as an oncogene to accelerate the progression of many cancers including colorectal cancer and hepatocellular carcinoma, but it has rarely been reported in LUAD." (PMID 36864456, 2023). "In colorectal cancer, a new mechanism for SNHG15 was found: this lncRNA binds to the zinc-finger domain of SLUG and prevents its ubiquitination." (PMID 32318335, 2020). "For example, UICLM, LINC00657 and SNHG15 were reported to facilitate cancer development via serving as miRNAs sponges in colorectal carcinoma, esophageal squamous cell carcinoma and papillary thyroid carcinoma." (PMID 32976115, 2020). "However, the signalling pathways involved in in HCC, PDAC, and colorectal cancer remain unclear; therefore, additional studies are needed to explore the potential mechanisms by which SNHG15 expression predicts survival across diverse malignancies." (PMID 33243205, 2020). "Besides, SNHG15 could promote cell proliferation, invasion and drug resistance in colorectal cancer, suggesting its potential as prognostic marker and target for RNA-based therapies." (PMID 32126023, 2020). "Assays have confirmed that SNHG15 interacts with AIF based on protein translation, and then participates in the stress response of colorectal cancer cells to 5-FU." (PMID 37056344, 2023). "In colorectal cancer (CRC) cells, the elevated expression of SNHG15 was observed to be contributed to the cell proliferation, invasion and 5-Fu resistance, but the oncological effects of SNHG15 in CRC could be partly weaken with the high expression of miR-141." (PMID 32633324, 2020). "Furthermore, SNHG15 enhances tumour development or drug resistance in glioblastoma multiforme, colorectal carcinoma, and prostate cancer through the SNHG15/CDK6/miR-627, SNHG15/miR-141/SIRT1/Wnt/β-catenin, SNHG15/miR-338-3p/FKBP1A, and SNHG15/miR-338-3p/FOS-RAB14 axes." (PMID 33243205, 2020).